SOCS3 (suppressor of cytokine signaling 3)
Diseases named in the same sentence as SOCS3 in open-access papers (continued):
Sharing a sentence is not in itself a finding about the gene and the disease.
cancer (continued). "Methylation silencing of the SOCS3 in HCC may result in survival cancer cells via upregulation of cytokine signaling pathways and resistance to apoptosis, which in turn lead to unfavorable response to TACE treatment." (PMID 28404963, 2017). "SOCS3 is frequently silenced in cancer, thereby leading to a growth advantage for cancer cells." (PMID 28228755, 2017). "Therefore, SOCS3 is a vital regulator of several diseases including atopic, autoimmune and infectious diseases, inflammation, and cancer development." (PMID 28179578, 2017). "Recently, more and more studies focus on the anti-cancer effect of SOCS3." (PMID 28969053, 2017). "To summarize, suppression of STAT3 and activation of SOCS3 would inhibit cancer cell growth." (PMID 26982332, 2016). "Restoring SOCS3 expression through demethylation in such cancer cells may successfully suppress tumorigenesis." (PMID 25695729, 2015). "The slight induction of MMP—2 expression by cancer could possibly be the result of SOCS3 mediated IL—6 pathway inhibition." (PMID 25789991, 2015). "Hypermethylation-mediated silencing of SOCS3 has been identified in multiple types of cancer." (PMID 25695729, 2015). "The role of SOCS3 in various types of cancer is controversial." (PMID 23028842, 2012). "Considering the role of SOCS3 in HNSCC cell proliferation, migration and invasion in vitro and the fact that some cancer cell lines retained endogenous expression of SOCS3, we next wanted to assess its expression in HNSCC according to the size and grade of the tumors." (PMID 23028842, 2012). "MiRNA downregulation of SOCS3 in smokers without COPD might contribute to the risk of developing cancer in these patients." (PMID 38533493, 2024). "Thus, the anti-oxidative and -proteolytic role of NRF2 and its upstream signals such as SOCS3 may warrant detailed studies in cancer cachexia, especially its early (precancerous) inflammatory stages, as presently detected." (PMID 35626644, 2022). "Indeed, the inhibition of STAT3 and SOCS3 has been shown to reverse cancer-related muscle wasting." (PMID 35626644, 2022). "Therefore, this study aims to further discuss the molecules and signal pathways regulating the expression and function of SOCS1 and SOCS3 in various types of cancers and elucidate the feasibility and efficiency of SOCS-based target therapeutic strategy in anticancer treatment." (PMID 28228755, 2017). "Therefore, this raises the question of whether signaling involving SOCS3 may crosstalk with myogenic pathways under chronic IL-6 stimulation during cancer cachexia." (PMID 22361433, 2012). "In addition critical roles for pSTAT3 and SOCS3 in cancer have also been proposed." (PMID 20553623, 2010). "This leads to the degradation of SOCS3, a substrate receptor of CRL5, and the subsequent accumulation of its substrate, integrin β1, ultimately promoting cancer metastasis." (PMID 41159544, 2026). "Additionally, miRNA-mediated downregulation of SOCS3 in smokers without COPD may increase their susceptibility to developing cancer." (PMID 40191199, 2025). "The results indicated that the promoter methylation levels of SOCS1 (p– = 7.379E‐07), SOCS3 (p = 4.534E‐10), SOCS5 (p = 1E‐12), SOCS6 (p = 5.534E‐11), and CISH (2.273E‐05) were lower in cancer tissues than in normal tissues." (PMID 39307915, 2024). "Through suppressors of cytokine signaling 3 (SOCS3), adiponectin inhibits the activation of STAT3, which promotes the proliferation, survival, and invasion of cancer cells." (PMID 38255203, 2024). "All the other genes (ATF3, EMP1, GADD45B, SOCS3, and ZFP36), distinct from EGR3, have been independently demonstrated to function as migration inhibitors in cancer cells." (PMID 38543002, 2024). "Aberrant methylation of the CpG of SOCS3 promoters has been reported to result in increased phosphorylation and activation of STAT3 in cancers such as lung cancer and hepatocellular carcinoma." (PMID 38534772, 2024).
cancer (continued). "By analyzing cancer genome atlas datasets, a study revealed a correlation between the expression of SOCS1 and SOCS3 and the prognosis of HCC patients, where high expression of SOCS1 was associated with a favorable prognosis." (PMID 39307915, 2024). "Knockdown of SOCS3 reversed the repressive impacts of miR-92a inhibitors on self-renewal and growth of CRC cancer stem cells." (PMID 35184640, 2022). "SOCS3 can repress the JAK-STAT pathway, inhibit cancer cell malignant transformation, and facilitate cancer cell apoptosis." (PMID 35184640, 2022). "Then, to finalize the genes and protein products in question, we evaluated the crucial genes in the GEPIA database and finally confirmed MYLK, SOCS3, STAT5B, BIRC5, PLK1, and RAPGAP1 proteins significantly in this cancer database." (PMID 35928368, 2022). "Previous reports have stated that the SOCS3/JAK2/STAT3 axis modulates the occurrence and development of various cancers." (PMID 34388111, 2021). "Several previous studies have shown that IGFBP3, SOCS3, and MMP14 are related to radiosensitivity in certain types of cancers, which is consistent with our results that these three genes were highly expressed in radioresistant cells." (PMID 34638754, 2021). "In this study, we identified SOCS3 as the key SOCS family member involved in the suppression of IL-22 signaling in healthy and transformed cultured keratinocytes, and in vivo in a cancer mouse model of SCC." (PMID 28445952, 2017). "Tumbar and the colleagues reported that transcriptional repression of SOCS3 and SOCS4 by RUNX1 were essential for cancer cell growth in oral, skin, and ovarian epithelial human cancer cells." (PMID 28750679, 2017). "Aberrant methylation of tumor suppressor genes (TSG) such as SOCS-1, SOCS-3, SHP-1, and PRG2 has been documented in a variety of cancers including hematological malignancies, and is a plausible means by which cells can acquire therapy resistance." (PMID 26547689, 2015). "Immunoreactivity for SOCS-3 was similar to that for CIS, with carcinoma staining more prominent than in normal epithelium, although staining in blood vessels was not as evident (panels B1 and B2)." (PMID 12888825, 2003). "In cytotoxic T cells/NK cells, we found that SUDV-induced IL-6 was predicted to induce SOCS3 expression and the downstream suppression of STAT5, granzyme B (GZMB) and PRF1 expression, leading to suppressed apoptosis of APCs and cancer cells, as well as pore formation." (PMID 41181097, 2025). "Cancers that have low IL-6R/STAT3 expression and delayed SOCS3 feedback may alternate metabolic activity in a manner similar to MIA PaCa-2." (PMID 38141171, 2024). "Finally, lncRNA DANCR showed the ability to support EMT, cancer stemness, and inflammation in BC cells in vitro by promoting the binding of EZH2 to the SOCS3 promoter, thereby inhibiting its expression." (PMID 37275549, 2023). "Mechanistically, Kremen2 may exert its oncogenic effect by interacting with SOCS3 and blocking the ubiquitin-dependent EGFR degradation, thereby sustaining the EGFR-mediated cancer signaling pathways and promoting cell proliferation and metastasis of NSCLC." (PMID 37270563, 2023). "To effectively relieve pain and not influence cancer treatment, we utilized synthesized miRNA-30a-5p inhibitor to directly suppress miRNA-30a-5p and subsequently increase the level of SOCS3." (PMID 35093117, 2022). "Although several studies have currently shown the correlations between SOCS3 and several types of cancer, no pan-cancer analysis is available to date." (PMID 35600392, 2022). "Furthermore, the deregulation of miR-221-3p expression is involved in the regulation of the suppressor of cytokine signaling 3/signal transducer and activator of transcription 3 (SOCS3/STAT3) pathway, which is particularly relevant in cancer resistance." (PMID 35681658, 2022).
cancer (continued). "As our results suggested that PD-L1 and SOCS3 are negatively correlated in HCC tissues, and it still remains ambiguous whether SOCS3 can selectively down-regulate PD-L1 to promote anti-cancer immune responses in HCC." (PMID 32742491, 2020). "By monitoring the phenotypes of these cells, we found that overexpression of SOCS3 rescued multiple malignant phenotypes induced by DANCR in both MCF10A and MCF7 cells, including cell viability, migration, invasion, EMT, and cancer stemness." (PMID 31860165, 2020). "Both epigenetic suppression of SOCS3 and the paracrine signals in the TME may contribute to the sustaining stimulus for STAT-3 activation in multiple forms of cancer." (PMID 32855767, 2020). "In STAT3 driven cancers, SOCS3 seems to be the most important negative feedback regulator and mouse models of SOCS3 ablation show strong STAT3 activation." (PMID 31557897, 2019). "The OD value measured by MTT assay showed that upregulation of SOCS3 could inhibit the proliferation rate of HCC cells, but as the upstream miR-221-3p is suppressed, the proliferation ability of cancer cells decreased." (PMID 31222560, 2019). "Furthermore, the suppressor of cytokine signaling 3 (SOCS3), which is able to inhibit p42/p44 MAPK signaling and the proliferation and migratory ability of cancer cells, is upregulated upon LXR activation." (PMID 30154328, 2018). "The negative regulator SOCS3 is a key player in the modulation of the JAK/STAT signaling that control a number of inflammatory cytokines such as IL6 and IL16 and is involved in infectious diseases and cancers." (PMID 28179578, 2017). "It is known that the activation of STAT3 in cancers leads to gene expression promoting cell proliferation and resistance to apoptosis, but 15d-PGJ2-induced SOCS3 overexpression may have prevented STAT3 phosphorylation." (PMID 27190500, 2016). "In summary, low levels of SOCS3 do not appear to be involved in the induction of IDO by IL-6 in the human cancer cells and tissues analyzed." (PMID 24657910, 2014). "In non-carcinoma HES cells, SOCS3 protein increased after addition of IL11 from 1-500 ng/ml." (PMID 20553623, 2010). "Downregulation of SOCS3, by miRNA, in smokers without COPD might contribute to the risk of developing cancer in these patients." (PMID 38533493, 2024). "However, anticancer drugs activated by NRF2-induced enzymes such as NQO1 could be exploited in SOCS1-low/SOCS3-high HCC and other instances of NRF2-mediated cancer progression." (PMID 36765862, 2023). "However, this miR-221-3p-SOCS3 axis is not a novel regulatory axis in cancer, but it was not confirmed in OS by a previous study." (PMID 34388111, 2021). "The exogenous expression of PTPRD in human GBM and other cancer cell lines inhibited cell growth, which coincided with a substantial decrease in the expression levels of phosphorylated STAT3 (Y705) and, consequently, one of its downstream targets, suppressor of cytokine signaling 3 (SOCS3)." (PMID 30208623, 2018). "However, in this study, only LXRα was demonstrated to affect the level of SOCS3, indicating that the LXRα-mediated induction of SOCS3 is responsible for the anti-HCC effects of LXR agonists even though LXRβ has the function of anti-cancer." (PMID 28969053, 2017). "RORC1 was shown to drive cancer-induced emergency myelopoiesis by affecting other crucial transcription factors regulating myelopoiesis, e.g., C/EBPβ (CCAAT-enhancer-binding protein-β) and SOCS3 (suppressor of cytokine signaling 3), acting downstream of the CSFs." (PMID 27690299, 2017). "Negative modulation of SOCS1 and SOCS3 is a survival strategy in most cancer cells." (PMID 27190500, 2016). "Liver SOCS3 mRNA expression was induced by cancer in non-cachectic mice." (PMID 25789991, 2015).
cancer (continued). "We then asked if STAT3 de-phosphorylation by 5-AZA could correlate with the upregulation of SOCS3 and/or PTPN6, as the former is a JAK/STAT inhibitor and the latter is a tyrosine phosphatase whose promoter methylation has been shown to contribute to STAT3 activation in other cancers." (PMID 38534772, 2024). "Moreover, our results about SOCS3 are in agreement with previous studies that have hypothesised the relationship between the methylation of the SOCS3 promoter and poor prognosis in GBM, and its low expression and worse response in other cancers." (PMID 30811476, 2019). "Additionally, future studies investigating how FXR modulates SOCS3 and consequently impacts STAT3 signaling in CSCs could facilitate the development of more effective treatments aimed at disrupting the CSCs, ultimately improving patient outcomes across various cancer types." (PMID 39940889, 2025). "Cancer tissues exhibited a lower level mRNA expression of SOCS-1 and SOCS-3 than percarcinoma tissues, however this difference was not statistically significant." (PMID 30788302, 2018). "The apoptotic mechanism of cancer cells promoted by genipin is related to the negative regulation of Mcl-1, which can occur through the activation of the SHP-1 phosphatase and the suppressor of cytokine signaling 3 (SOCS3)." (PMID 32858815, 2020). "However, other predicted targets such as SOCS3, PTPRN2, MMP3, PRG1 and BASP1 have not yet been experimentally validated but could be of particular interest on cancer research." (PMID 28346474, 2017).
infection (162 papers, 2008 to 2025). The state of being infected such as from the introduction of a foreign agent such as serum, vaccine, antigenic substance or organism. "This transcriptional profile resembles interferon-stimulated neutrophil subsets previously observed in infection, autoimmunity, and chronic inflammation, pointing to a conserved inflammatory program engaged by Socs3 deficiency." (PMID 41333423, 2025). "Infection with HuCoV-OC43 caused an eight-fold induction of SOCS1 as well as SOCS3 (p < 0.01 for both), which was prevented in the presence of 30 μM pJAK2." (PMID 35799776, 2022). "DC-specific SOCS3 ablation resulted in increased susceptibility to infection as a result of reduced cross-talk with T cells." (PMID 34604264, 2021). "Our study does not support a role for diet-induced mild hypothalamic inflammation in the increased susceptibility to infection despite altered Nfkbia and Socs3 mRNA expression after the diet." (PMID 29760677, 2018). "Previously, SOCS3 in macrophages has been implicated in promoting the IL-12-dependent development of Th1 cells in experimental Toxoplasma gondii and Mtb infection." (PMID 29176982, 2017). "Others have demonstrated that MCMV infection in macrophages in vitro causes an increase in SOCS1 and SOCS3 mRNA expression levels from 2 to 24 hours after infection." (PMID 28182772, 2017). "Our current study also indicates that kallistatin attenuated inflammation and organ injury in association with increased SOCS3 expression in the lung and kidney of mice with polymicrobial infection or LPS-induced endotoxic shock." (PMID 25930108, 2015). "Health traits:SOCS3 is associated with somatic cell score trait in cattle and is expressed in goat milk fat globules in response to experimental intramammary infection with Staphylococcus aureus." (PMID 26083354, 2015). "γδ+ T cells’ numbers in SOCS3-deficient mice were increased (independently of infection) and accounted for the exacerbated susceptibility to disease of these mutant mice." (PMID 24600449, 2014). "All Socs3fl/fl LysM cre, Socs3fl/fl lck cre (with SOCS3-deficient T cells), and gp130F/F mice showed increased susceptibility to infection with M. tuberculosis." (PMID 24600449, 2014). "All Socs3fl/fl LysM cre, Socs3fl/fl lck cre (with SOCS3-deficient myeloid and lymphoid cells, respectively) and gp130F/F mice, with a mutation in gp130 that impedes binding to SOCS3, showed increased susceptibility to infection with M. tuberculosis." (PMID 23853585, 2013). "Mice deficient in the expression of SOCS3 either in myeloid or lymphoid cells were extremely susceptible to infection with M. tuberculosis as measured by elevated bacterial levels, worsened pathology and reduced survival." (PMID 23853585, 2013). "First indications for beneficial effects of SOCS-3 gene expression on viral replication came from studies using the HCV core protein as a replacement for the influenza A viral NS1 in the context of infections with a NS1 deficient influenza virus." (PMID 18989459, 2008). "The underlying consequence for the induction of SOCS1 and SOCS3 by Chlamydia may be a mechanistic ploy to limit its inflammation during early infection for perpetuation and survival in the host." (PMID 32684836, 2020). "Infection‐induced IDO protein is enhanced in SOCS3 deficient and sufficient‐mucosa." (PMID 28508554, 2017). "The molecular mechanism underlying the SOCS-3 inhibition during infection probably occurred through the induction of mRNA-203, a small single-stranded noncoding RNA that can suppress SOCS-3 expression at both mRNA and protein levels by binding to the 3ʹ non-translated region of SOCS-3 mRNA." (PMID 28748038, 2017). "Indeed, the computed top DEG, typifying each cluster on day 3 in the effector phase of infection, hosted several interferon-induced anti-viral genes (Irf1, Irf7, Ifrd1, Socs1, Socs3, Ifit1, Bst2, and Isg15) as well as genes associated with mature resident Trm cells (Cd69, Nfkbid, Brd2, FosB)." (PMID 35260804, 2022).